IL19 (interleukin 19)
Diseases named in the same sentence as IL19 in open-access papers (continued):
Sharing a sentence is not in itself a finding about the gene and the disease.
steatosis (1 paper, 2021). Increased lipid within the cytoplasm of cells. "In order to clarify the mechanism of action of IL-19, we conducted further experiments using in vitro steatosis models in HepG2 cells." (PMID 34944021, 2021). "We firstly observed that a diet-induced steatosis and fibrosis was exacerbated in IL-19 KO mice." (PMID 34944021, 2021). "In vitro models of steatosis using HepG2 cells revealed novel effects of IL-19." (PMID 34944021, 2021). "The action of IL-19 may control steatosis formation, fibrosis formation, or both." (PMID 34944021, 2021). "In IL-19 KO mice fed a CDAHFD diet, the size of droplets was intermediate, similar to WT mice, but steatosis was significantly weaker than WT mice." (PMID 34944021, 2021). "A further detailed comparison of the results of WT and IL-19 KO mice showed that liver weight and steatosis were milder in IL-19 KO mice than in WT mice, and increases in ALT and pro-inflammatory cytokines were worse in IL-19 KO mice than in WT mice." (PMID 34944021, 2021). "Importantly, IL-19 KO mice showed marked fibrosis in addition to increased liver weight, increased ALT, increased pro-inflammatory cytokines, and marked steatosis." (PMID 34944021, 2021).
type 2 diabetes (1 paper, 2018). "The measurement conducted on healthy control subjects revealed smaller IL-19 concentration (mean = 13.2 pg/ml) than on subjects with type 2 diabetes (mean = 40.5 pg/ml), since IL-19 is only expressed in inflammatory location and condition." (PMID 29805787, 2018).
tumor (30 papers, 2013 to 2025). "IL19 is a pro-inflammatory cytokine that has been associated with tumor progression and immune modulation in several malignancies." (PMID 40647365, 2025). "IL-19 blockade promoted T cell activation and reprogrammed tumor-associated macrophages toward weakened pro-tumoral phenotypes with reduced Arginase 1 expression." (PMID 40057744, 2025). "The study reported by Chung-Hsi Hsing showed that of the IDC specimens, Elevated tumour metastasis, advanced tumour stage, and poor survival were all linked to high IL-19 expression." (PMID 37675062, 2023). "The IL-19 expression in BC tissue is linked with an increased mitotic rate leading to worse metastasis-free survival, disease-specific survival, high grade tumor metastasis, and worse prognosis." (PMID 37675062, 2023). "IL-19 levels have been verified to be associated with primary tumor status, advanced tumor stage, a high degree of occurrence of lymph node and distant metastasis, HER2 status, and the presence of mitotic figures." (PMID 23710200, 2013). "We utilized clinical and genomic data from the Taiwan GBM cohort and The Cancer Genome Atlas (TCGA) to analyze RNA sequencing data from patient tumor samples, determining the association of interleukin-19 (Il-19) expression with survival and immunosuppressive activity." (PMID 40057744, 2025). "We also examined the association of IL-19 with tumor stroma in Bc." (PMID 37675062, 2023). "High IL-19 levels are associated with poor prognosis, metastasis, and advanced tumor stages." (PMID 36726488, 2023). "Previous studies revealed IL-19 association with tumor metastasis and poor clinical outcomes." (PMID 36726488, 2023). "However, we did find the clinicopathological variables correlated to IL-19 expression; high IL-19 expression associated with advanced tumor stages." (PMID 24130695, 2013). "Similarly, in BC, high IL-19 expression in tumor tissue is associated with poor clinical outcomes." (PMID 40806452, 2025). "Cytokine array and single-cell RNA sequencing were used to examine the effects of IL-19 blockade on tumor immune microenvironment, including tumor-infiltrating leukocyte profiles, differentiation and immunosuppressive genes expression in tumor associated macrophages (TAM)." (PMID 40057744, 2025). "We demonstrated that blocking IL-19 significantly suppressed tumor progression in both TMZ-sensitive and TMZ-resistant GBM cells." (PMID 40057744, 2025). "Blocking IL-19 significantly inhibited tumor progression of both TMZ-sensitive (TMZ-S) and TMZ-resistant (TMZ-R) GBM-bearing mice, and modulated the immune response within the GBM microenvironment." (PMID 40057744, 2025). "Unlike Arg1 and STAT3 inhibitors, which generally aim to suppress specific immune-suppressive pathways, IL-19 antibody therapy directly modulates the tumor microenvironment by addressing aberrant cytokine signaling." (PMID 40057744, 2025). "CRISPR Il-19−/− cell lines and Il-19−/− mice were used to examine the role of IL-19 in tumor invasion and M2-like macrophage-mediated immunosuppression." (PMID 40057744, 2025). "In this study, we demonstrated the immunosuppressive function of IL-19 in the GBM tumor microenvironment through single-cell RNA sequencing (scRNA-seq) analysis." (PMID 40057744, 2025). "By neutralizing IL-19, this therapy can potentially reprogram the immune system to enhance anti-tumor responses, counteracting the immunosuppressive milieu commonly observed in GBM." (PMID 40057744, 2025). "In summary, our study demonstrate that IL-19 is a potential theranostic target to ablate immune suppression and tumor invasion in GBM." (PMID 40057744, 2025). "A Treg-like subset (C8_CD4T_2), which is enriched in TMZ-resistant tumors, was decreased, while a γδ T cell cluster with antitumor activity was significantly increased in IL-19 antibody-treated GL261/TMZ-resistant tumor-bearing mice." (PMID 40057744, 2025).
tumor (continued). "High expression of IL-19 in tumor tissue has been found to correlate with tumor metastasis and clinical staging." (PMID 40806452, 2025). "In conclusion, silencing IL-19 weakens the immunosuppressive activity of TAMs and slows tumor progression in GBM." (PMID 40057744, 2025). "For the intrinsic IL-19 role in tumor cells, IL-19 is a pro-tumor cytokine that promotes GBM cell migration and invasion through the AKT/β-catenin/WISP1 pathway." (PMID 40057744, 2025). "In comparison to non-tumor samples, it was observed that the protein levels of TGFβ-1, IL19, CXCR4, BMP1, VCAN, and WNT2 were significantly enhanced in several tumor samples." (PMID 41348904, 2025). "Patients with GBM with high Il-19 expression levels in tumor tissues had lower survival rates than those with low expression levels according to RNA-seq and microarray data." (PMID 40057744, 2025). "The number of Ki67+ cells in shIL-19 GSC-derived tumors was less than that in shLacZ tumors, suggesting that tumor-derived IL-19 positively regulates tumor cell proliferation." (PMID 40057744, 2025). "RNA microarray analysis also revealed that WISP1 expression levels were considerably higher in human tumor tissues with high Il-19 expression than in those with low Il-19 expression." (PMID 40057744, 2025). "Tumor cells stimulate osteoclasts to release the ligand interleukin (IL)-19 for the IL receptor 20 subunit β (IL-20RB), which then triggers IL-20RB-expressing tumor cells to initiate downstream JAK1/STAT3 signaling." (PMID 39512767, 2024). "In consequence, phosphorylated STAT3 translocates to the nucleus of tumor cells promoting the secretion of granulocyte-macrophage colony stimulating factor (GM-CSF), a cytokine that induces IL-19 synthesis in osteoclasts." (PMID 39737401, 2024). "During this process, tumor cells stimulate osteoclasts to release IL-19, which acts as the ligand for IL-20RB." (PMID 38260135, 2023). "In BC, Il-19 has an autocrine action and offers an environment for tumor development, proliferation, migration, and metastasis." (PMID 37675062, 2023). "In 4 T1 cells having IL-19 knockdown, endogenous fibronectin expression, and tumour cell movement are confirmed, and treatment with IL-19 further boosts metastasis in IL-19 knockdown cells." (PMID 37675062, 2023). "The in-vivo and in-vitro studies have also reflected that upregulation of IL-19 enhances tumor development and affects clinical outcomes in BC patients through several pathways including the JAK TAT signalling pathway." (PMID 37675062, 2023). "Overall, our study indicates that IL-19 increases tumour growth and that inhibiting it in addition to standard treatments will greatly improve BC patient’s therapeutic responses." (PMID 37675062, 2023). "Overall, there is evidence that IL19, either derived from the environment or by an autocrine release by tumor cells, seems to impair the course and clinical outcome of ER-positive BC disease." (PMID 35298675, 2022). "IL-20RB–promoted tumor proliferation in bone metastases was also diminished by Il19 KO of host mice." (PMID 36006737, 2022). "Mechanistically, tumor cells induced osteoclasts to secrete the IL-20RB ligand IL-19, and IL-19 stimulated IL-20RB–expressing tumor cells to activate downstream JAK1/STAT3 signaling, leading to enhanced proliferation of tumor cells in bone." (PMID 36006737, 2022). "The IL-19–neutralizing antibody effectively blocked osteoclast-induced STAT3 activation in IL20RB-expressing tumor cells." (PMID 36006737, 2022). "In humans, IL19 drives pathogenesis of BC and promotes tumor progression by paracrine and autocrine activities." (PMID 35298675, 2022). "IL-19 has an autocrine effect on breast cancer cells by directly promoting proliferation and migration of tumor cells while indirectly providing a microenvironment for tumor progression." (PMID 25682197, 2015).
tumor (continued). "We also found that several types of tumor cells expressed IL-19, especially in squamous cell carcinoma of the skin, tongue, esophagus, and lung." (PMID 24130695, 2013). "Although IL-24 was reported to be a tumor suppressor, the biological functions of IL-19 and IL-24 are different." (PMID 24130695, 2013). "Endogenous fibronectin expression and tumor cell migration are substantiated in IL-19-knockdown 4T1 cells, and treatment of IL-19 further increases migration in IL-19-knockdown cells." (PMID 23710200, 2013). "In general, we found that the entire family of IL-10 cytokines including IL-10, IL-19, IL-20, IL-22 and IL-24 was increased in tumor compared to normal skin." (PMID 23667456, 2013). "We injected SCID mice with CE81T cells and then treated them with anti-IL-19 mAb or control IgG every 3 days and determined tumor growth for 32 days." (PMID 24130695, 2013). "Elevated IL-19 levels were also closely correlated with inflammatory cell components, which accounted for tumor progression and metastasis." (PMID 23710200, 2013). "Knockdown of endogenous IL-19 in tumor cells inhibited FN expression and assembly, but overexpression of IL-19 induced FN production." (PMID 23710200, 2013). "Additional investigation of the activation of the type I IL-20 receptor complex by both IL-19 and IL-24 and the subsequent intracellular responses in tumor cells is needed." (PMID 24130695, 2013). "A strong correlation was substantiated between IL-19 expression with primary tumor status (T) (P = 0.019), nodal status (P = 0.034), distant metastasis (P = 0.014) and high tumor stage (P = 0.035)." (PMID 24130695, 2013). "IL-19 expression in tumor cells has been investigated using tissue microarray technology and an immunohistochemical survey with an anti-IL-19 monoclonal antibody in 15 neoplastic tissue types." (PMID 23710200, 2013). "This suggests that therapeutic strategies combining IL-19 blockade with immune checkpoint inhibitors or adoptive T-cell therapies could synergistically disrupt immunosuppressive mechanisms within the tumor microenvironment." (PMID 40057744, 2025). "Moreover, IL-19 contributes to an immunosuppressive tumor microenvironment by promoting the polarization of tumor-associated macrophages (TAMs) toward the M2 phenotype, which supports tumor growth and suppresses anti-tumor immune responses." (PMID 40806452, 2025). "In 3D spheroid co-cultures, TOPK knockdown in fibroblasts reduce cSCC colony size and number, likely by attenuating the production of pro-tumorigenic factors (e.g., IL19, matrix metalloproteinases) that normally facilitate tumor cell expansion and ECM remodeling." (PMID 40647365, 2025). "Due to its immunosuppressive activity, IL-19 could serve as an immunoregulatory cytokine by dampening antigen-presenting capacity and regulating M2 macrophage polarization in the tumor microenvironment." (PMID 40057744, 2025). "Additionally, positive IL-19 staining was observed in various tumor cells, notably in squamous cell carcinoma (SCC) of the skin, tongue, esophagus, and lung." (PMID 40806452, 2025). "This epidermal-to-dermal signaling axis is reinforced by our finding that chronic TGFβ treatment, a hallmark of advanced tumor microenvironments, upregulates IL19 in fibroblasts, suggesting a feedforward loop where stromal IL19 further amplifies TOPK activity in adjacent tumor cells." (PMID 40647365, 2025). "In addition to the role of the WISP1/AKT axis in M2 macrophages within the GBM tumor microenvironment, this study identifies IL-19 as a positive regulator of the AKT/WISP1 axis in TMZ-resistant GBM invasion." (PMID 40057744, 2025). "Our human GBM tumor tissue and cytokine array analysis indicate that IL-19 act as an immunosuppressive cytokine in tumor, however, the mechanism of IL-19 in modulation of immune response in GBM remains unclear." (PMID 40057744, 2025).
tumor (continued). "Although this blocking effect did not affect Arg1 expression in TMZ-resistant GBM tumor, blocking IL-19 still can downregulate the expression of STAT3-associated immunosuppressive genes (CD274 and S100A4) in both TMZ-sensitive and TMZ-resistant GBM tumor." (PMID 40057744, 2025). "Furthermore, the conjugation of IL-19 antibodies to the nanoparticles enables precise targeting of IL-19-expressing tumor cells." (PMID 40057744, 2025). "Additionally, M2-like cells (CD206+) and macrophage/microglia (Iba1+) also expressed IL-19 in the intratumoral region of tumor tissue from patients with GBM." (PMID 40057744, 2025). "IL-19 is primarily involved in promoting an anti-inflammatory environment, which may facilitate tumor growth and metastasis." (PMID 40806452, 2025). "Targeting TOPK and IL19 simultaneously may provide a more effective strategy to inhibit both tumor growth and the supportive tumor microenvironment." (PMID 40647365, 2025). "Thus, we knocked down IL-19 in GSCs and found that the tumor volume of shIL-19 GSC-derived tumors was smaller than that of shLacZ tumors 13 days post-GSC inoculation." (PMID 40057744, 2025). "Consequently, IL-19 promotes the activation of IL-20RB-expressing tumor cells, activating the JAK1/signal transducer and activating the transcription 3 (STAT3) signaling pathway." (PMID 38260135, 2023). "Furthermore, BC cells are encouraged to proliferate, migrate, develop tumours, and metastasize when IL-19 is overexpressed." (PMID 37675062, 2023). "Augmented IL-19 expression has been related to poorer clinical outcomes for patients with BC and directly enhances proliferation and migration while also serving as a microenvironment for tumour formation." (PMID 37675062, 2023). "Interestingly, when osteoclasts were incubated in tumor cell CM, IL-19 secretion by osteoclasts was enhanced by CM of both A549 and HBM1." (PMID 36006737, 2022). "Interestingly, the six ALCL patients with upregulated PDGFRB expression also showed a downregulation of IL-19 and an upregulation of IL-10 mRNA levels in tumor cells compared to healthy control cells." (PMID 36045346, 2022). "In addition, STAT3 inhibitors, including stattic and napabucasin, suppressed STAT3 phosphorylation and activation in IL20RB-expressing tumor cells after stimulation by osteoclastic CM or IL-19, leading to inhibition of organoid formation." (PMID 36006737, 2022). "Osteoclast-secreted IL-19 primes proliferation of IL-20RB–expressing tumor cells." (PMID 36006737, 2022). "Interestingly, tumor cells with strong or weak metastatic proclivities can all induce IL-19 secretion of osteoclasts, but their responsiveness toward osteoclasts is dependent on IL-20RB expression." (PMID 36006737, 2022). "Moreover, IL19 enhances tumor growth and metastasis of ER-positive BC in preclinical in-vivo models." (PMID 35298675, 2022). "Osteoclast-secreted IL-19 activates JAK1/STAT3 signaling in IL20RB-expressing tumor cells." (PMID 36006737, 2022). "Confirming this hypothesis, administration of an IL-19–neutralizing antibody in the osteoclastic CM blocked the effect of CM in promoting organoid formation of IL20RB-expressing tumor cells." (PMID 36006737, 2022). "IL20RB knockdown impaired the responsiveness of tumor cells to recombinant IL-19." (PMID 36006737, 2022). "First, ligand targeting using an IL-19–neutralizing antibody markedly abolished osteoclast-induced tumor proliferation in vitro, but the in vivo efficacy, and more importantly, the possible side effects of targeting stromal-derived factors are yet to be further investigated." (PMID 36006737, 2022). "Additionally, the potential role of IL-19 for assessing tumor staging, tumor aggressiveness, and disease progression is discussed." (PMID 23710200, 2013). "Whether tumor cell-derived IL-19 in driving in vivo tumor progression remains unaddressed." (PMID 40057744, 2025).